CD44 (CD44 molecule (IN blood group))
Diseases named in the same sentence as CD44 in open-access papers (continued):
Sharing a sentence is not in itself a finding about the gene and the disease.
Obesity (continued). "The consequence is that the ECM remodelling associated with obesity may be maladaptive, resulting in the accumulation of ECM molecules and the activation of ECM membrane receptors (e.g. integrins and CD44)." (PMID 37383542, 2023). "Since CD44 was able to reduce adiposity in C3H/HeJ mice, we can infer that the mechanism underlying obesity resistance in CD44-deficient mice is not driven solely by the inflammatory response of the TLR4 pathway." (PMID 35410390, 2022). "Our current study investigates our hypothesis that CD44 is a critical mediator of obesity and metabolic syndrome." (PMID 35410390, 2022). "CD44 is a candidate gene for obesity and diabetes development and may be a critical mediator of a systemic inflammation associated with obesity and diabetes." (PMID 35410390, 2022). "Nevertheless, knowing the precise effects of HA fragments on blood leukocyte behavior through their interaction with CD44 are at present unknown and need further studies in the setting of obesity." (PMID 35896710, 2022). "These metabolic phenotypes are exactly opposite to those in GPNMB-KO mice we described in this study and therefore further support a critical interaction of GPNMB with CD44 to elicit its beneficial anti-inflammatory functions to preserve metabolic homeostasis in obesity." (PMID 34582891, 2021). "We next asked whether obesity was increasing the rates of cell death in CD44+CD4+ TILs from DIO mice, again focusing on the day 21 time point." (PMID 34064933, 2021). "We showed that OPN could inhibit adipogenesis through inhibition of the C/EBP signal via integrin αν/β1 and CD44 and further attenuate obesity." (PMID 30911298, 2019). "Together, these results may suggest that PP enhances the usage of CD44 to develop immune-metabolic responses to preserve liver function in obesity." (PMID 30134638, 2018). "Taken together, our results suggest that CD44 may play a critical role in linking obesity to the development of insulin resistance by promoting hepatic steatosis and the infiltration of macrophages in adipose tissue." (PMID 23505504, 2013). "Recent studies showed that obesity-induced hepatic steatosis and WAT-associated inflammation are accompanied with increased CD44 expression and opened the possibility that CD44 might play a regulatory role in obesity and associated pathologies." (PMID 23505504, 2013). "The association of obesity and increased expression of CD44 in liver and WAT suggested that CD44 might have a role in regulating certain aspects of metabolic syndrome." (PMID 23505504, 2013). "In addition, antibody neutralization of CD44 reduces obesity-induced adipose tissue inflammation, as demonstrated by decreased expression of immune cell markers (CD68, F4/80, CD3e, and CD19), proinflammatory cytokines (TNF-α, IL-1β, IL-6, and IFN-γ), and monocyte chemoattractant protein-1 (MCP-1)." (PMID 37383542, 2023). "We report the effects of CD44 inactivation on adiposity, liver fat accumulation, and glucose tolerance in both male and female mice on C57BL/6J and C3H/HeJ genetic backgrounds to refine the mechanism(s) by which CD44 affects susceptibility to obesity and diabetes." (PMID 35410390, 2022). "However, the present findings provide evidence that regardless of the susceptibility of the background strain, CD44 deficiency was able to reduce diet-induced obesity in male mice." (PMID 35410390, 2022). "Either pharmacological or genetic ablation of HA, CD44, or RHAMM reverses these obesity-driven pathologies in vivo." (PMID 41301516, 2025). "Pharmacological and genetic disruptions of HA, CD44, or RHAMM prevents obesity-induced kidney damage." (PMID 41301516, 2025). "Obesity simultaneously promotes hyperactivation of CD8 tumor-infiltrating lymphocytes (TILs), as evidenced by increased expression of CD44, PD-1, Ki-67, IFNγ, and the death receptor Fas." (PMID 33123173, 2020).
Obesity (continued). "In addition, immunophenotyping revealed the increase of the surface expressions of CD44 and CD69 on various cell types, such as CD8+ and CD4 + T-cells, B-cells and macrophages, in animals with obesity." (PMID 39004641, 2024). "The effect of the secretome of CAAT isolated from patients with obesity and BC was investigated on the mRNA expression levels of CSC markers, such as CD24 and CD44 as well as EMT markers, such as vimentin and E-cadherin, was investigated in MDA-231 and SUM-149 cells using qRT-PCR." (PMID 35927653, 2022). "Osteopontin induces brown adipogenesis in cultured preadipocytes through the activation of the PI3K/Akt pathway in a CD44-dependent manner and the downregulation of OPN in WAT of mice exacerbates obesity and inhibits WAT browning via the inhibition of PPARγ-mediated activation of PI3K/Akt signaling." (PMID 35406450, 2022). "We then examined the functional capacity of CD44+CD4+ TILs, to determine whether obesity blunted their effector function in therapy-treated mice." (PMID 34064933, 2021). "We then examined the functional capacity of CD44+CD8+ TILs, to determine whether obesity blunted their effector function in therapy-treated mice." (PMID 34064933, 2021). "All animals analyzed were noted as healthy, with similar average body weights in aged CD44+/+ and CD44−/− mice, suggesting that obesity/body size or other apparent physical comorbidities did not impact the results." (PMID 32597007, 2020). "This hypothesis is consistent with recent reports showing that Opn mediates obesity-induced migration and infiltration of macrophages in WAT and this modulation appears to involve the CD44 pathway." (PMID 23505504, 2013). "Although this hypothesis seems to be contradicted by the elevated Cd44 in APOB/HSP females, a recent study revealed that CD44 inactivation in female mice had no detectable effects on several obesity-related symptoms, including adipose tissue inflammation." (PMID 40855499, 2025). "However, the role of HA and CD44 in regulating kidney function in the setting of obesity or ORKP has not been studied." (PMID 41301516, 2025). "It is currently unknown whether the favourably metabolic effects of CD44 deletion in obesity is through cell-autonomous actions or non-adipocytes, e.g. macrophages, and adipocytes interactions." (PMID 38692289, 2024). "In order to test this hypothesis, we used an obesity-susceptible strain of mice, C57BL/6J (B6), and an obesity-resistant strain, C3H/HeJ (C3H) with and without an inactivated, “knocked-out”, CD44 gene (CD44-KO)." (PMID 35410390, 2022).
squamous cell carcinoma (44 papers, 1998 to 2026). A carcinoma arising from squamous epithelial cells. "ALDH and CD44 expression were both associated with squamous cell carcinomas (χ2 test, p = 0.035 and p = 0.005, respectively)." (PMID 24091605, 2013). "CD44 expression was associated with squamous cell carcinoma but unexpectedly, a longer survival was observed in CD44-expressing adenocarcinomas." (PMID 21124918, 2010). "LUC10 was more efficiently sorted than LUC13, which could be due to the expression of CD44 being more strongly associated with the squamous cell carcinoma subtype than adenocarcinoma." (PMID 35806135, 2022). "The role of CD44 and splice variants as stem cell markers in squamous carcinomas remains to be fully confirmed and there are several alternative hypotheses to link such a constitutively and abundantly expressed molecule with stem cell-like properties." (PMID 22242150, 2012). "CD44 plays a role in various squamous cell carcinomas and has been shown to be mainly involved in EMT128 and cancer stemness." (PMID 38783892, 2024). "A decrease in HA and CD44 staining intensity or irregular staining with focal reduction in HA and CD44 have previously been reported in squamous cell carcinoma." (PMID 36359337, 2022). "The proportion of CD44+CD24low CSCs was determined by flow cytometry in cervical scrapings from 55 patients with squamous cell carcinoma of uterine cervix before treatment and after fractionated irradiation at a total dose of 10 Gy." (PMID 33535561, 2021). "The aim of this study was to evaluate the expression of TGF-B and CD44 in leukoplakia (premalignant lesion), squamous cell carcinoma (SCC), and normal oral mucosa to determine the role of these markers in the carcinogenesis process of the oral mucosa." (PMID 33681421, 2021). "In the same way, an increase of the expression of proteins, such as ECM1, CD9, and CD44 has been reported in EVs derived from squamous cell carcinoma cells upon mesenchymal transformation." (PMID 31453379, 2019). "UM-SCC-1 (University of Michigan Squamous Cell Carcinoma cell line) CAM xenografts contain CD44+ and ALDH+ cancer stem cell (CSC) proportions similar to UM-SCC-1 mouse xenografts supporting the applicability of the CAM assay for study of CSCs." (PMID 27117272, 2016). "Expression of CD44 marks a putative squamous cell carcinoma stem cell population, but only a minority of expressing cells with a basal phenotype have stem cell properties." (PMID 22242150, 2012). "Expression of alternatively spliced CD44 isoforms has been reported to correlate with poor prognosis in human squamous cell cancers, i.e. squamous cell cancer of the lung and cervix." (PMID 9792156, 1998). "In summary, the role of CD44 in squamous cell carcinoma could serve as a vital area for drug development and tumor marker." (PMID 38783892, 2024). "A study assessed immunohistochemical expression of CD44 in different grades of OSCC to evaluate its role in cancer progression showed an altered expression level of CD44 in OSCC with weak immunostaining in poorly differentiated squamous cell carcinoma." (PMID 32597160, 2020). "CD44 is known to cluster to the basal subtype, given its overexpression in squamous carcinoma." (PMID 29899832, 2018). "Moreover, the immunological properties of CD44-positive cancer stem-like cells have been compared with those of CD44-negative cells in squamous cell carcinoma of the head and neck." (PMID 26322272, 2015). "Furthermore CD44 expression is maintained throughout tumorigenesis in squamous cell carcinoma and bronchioloalveolar carcinoma, suggesting a histogenetic relationship between stem cells and their respective tumors." (PMID 21819617, 2011). "The aim of this study was to evaluate whether CD44 isoform expression is a prognostic factor in early-stage squamous cell cancer of the vulva." (PMID 9792156, 1998).
squamous cell carcinoma (continued). "However, its design principles—exploiting CD44 targeting and mucosal retention—are highly relevant for oral squamous cell carcinoma and may inform future intraoral formulations." (PMID 41012547, 2025). "In squamous cell carcinoma (SCC) cells, CD44 and PDPN colocalize on cell surface protrusions, and CD44 is required for PDPN to promote directional and sustained movement of epithelial cells." (PMID 35936713, 2022). "Tongue squamous cell carcinoma cells with UBE2C silencing exhibit lowered expression of the cancer stemness markers ALDH1/A2, CD44, CD166 and EpCAM, indicating the role of UBE2C in controlling the cancer stemness." (PMID 36551544, 2022). "CSC-like cells were established from three squamous cell carcinomas (SCC) and three adenocarcinomas (AC) of the lung and were shown to express common CSC markers such as Prominin-1, CD44-antigen, and Nestin." (PMID 33925297, 2021). "CD44 and ALDH expression pattern in Squamous Cell Carcinoma (SCC) and Adenocarcinoma (AC) of the lung." (PMID 24019906, 2013). "In vitro tests were performed on two different cell lines with different CD44 expression: NIH3T3 (mouse embryonic fibroblast cells, CD44-negative) and SCC7 (mouse squamous cell carcinoma cells, CD44-positive)." (PMID 23533773, 2013). "To determine the role of CD44 in esophageal cell invasion and EMT, we performed immunohistochemical staining of E-cadherin and CD44 on tissue microarrays of 166 squamous cell carcinoma (SCC) and 131 adenocarcinomas." (PMID 22069487, 2011). "Seventy cases of squamous cell carcinoma of the vulva International Federation of Gynaecology and Obstetrics (FIGO) stage I were examined immunohistochemically for expression of CD44 isoforms." (PMID 9792156, 1998). "Tongue squamous cell carcinoma cell lines treated with RSPO2 have higher numbers of the CD44+, CD133+, and ALDH+ CSC population, possess a high expression of CSC markers (CD133, OCT4, SOX2, and CD44), and exhibit increased sphere formation ability." (PMID 33946652, 2021). "Importantly, we noted that filopod formation was specifically inhibited in the presence of anti-RHAMM antibody, but not in the presence of anti-CD44 antibody, consistent with the reported stabilization of filopodia by RHAMM in squamous carcinoma cells." (PMID 34338608, 2021).
atherosclerosis (43 papers, 2008 to 2025). A disease characterized by the build-up of fatty material and calcium deposition in the arterial wall resulting in partial or complete occlusion of the arterial lumen. "Previous studies have linked CD44 to diseases marked by impaired angiogenesis and insulin resistance, such as atherosclerosis, aging, and endothelial cell senescence." (PMID 40260916, 2025). "Together, these data suggest that CD44 is directly implicated in prolonged inflammatory responses in many auto-inflammatory conditions such as atherosclerosis." (PMID 26029216, 2015). "We also identify several key genes within the module that are sensitive to altered Cd44 expression and likely to affect atherosclerosis risk." (PMID 25115202, 2014). "For this analysis we used all 666 brown module genes and found that only 1 gene, Cd44, was predicted to drive susceptibility to atherosclerosis." (PMID 25115202, 2014). "CD44 was reported to be a critical factor in inflammatory processes during wound healing, acute asthma, and atherosclerosis." (PMID 40389328, 2025). "The results of the gene expression analysis were validated with immunohistochemical Cd-44 staining of atherosclerotic lesions, which showed increased staining with the progression of atherosclerosis." (PMID 40278373, 2025). "CD44 promotes atherosclerosis by mediating inflammatory cell recruitment, vascular SMC activation, and phenotypic switching to a pro-inflammatory synthetic state." (PMID 40971695, 2025). "This regulatory mechanism is also involved in the COLLAGEN pathway and LAMININ pathways mediated by CD44, and immune infiltration increases in advanced atherosclerosis." (PMID 40824771, 2025). "This contrasts with a model of atherosclerosis, where Has3 loss led to an ECM-producing SMC phenotype - replicated in vitro by CD44 blocking - and was linked to increased plaque stability." (PMID 41280888, 2025). "Using a murine model of atherosclerosis, we demonstrate that this process is orchestrated by a progressively disrupted perivascular immune milieu characterized by an expansion of CD44+ memory CD4+ T cells at the expense of CD44− naive CD4+ T cells." (PMID 41143276, 2025). "Overexpression of the immune receptor CD44 activates inflammatory cells, while increased pro-inflammatory cytokines and oxidative stress exacerbate vascular endothelial activation, promoting atherosclerosis." (PMID 39598052, 2024). "The CD44 protein is highly expressed in the macrophages of patients with atherosclerosis, implying that CD44 can be used as a target of atherosclerosis macrophages." (PMID 36683743, 2023). "CD44 is an adhesion molecule that can recruit activated inflammatory cells adhere to blood vessels, thus promote atherosclerosis." (PMID 38268851, 2023). "Conversely, CD11c+CD44+ macrophages significantly increased with atherosclerosis from 3.8 ± 0.4% in WT to 26.3 ± 2.1% in ApoE−/− (HFD) mice." (PMID 35017526, 2022). "It is also worth mentioning that novel chemo-photothermal synergistic therapy targeted on CD44-positive inflammatory macrophages is being developed for the treatment of atherosclerosis." (PMID 35620523, 2022). "CD44 is believed to be involved in tumour growth and metastasis, proliferative diabetic retinopathy and atherosclerosis." (PMID 36409751, 2022). "Endothelial cell senescence contributes to the progression of atherosclerosis through increased and chronic adhesion to monocytes, due to demethylation of the CD44 promoter and increased expression of CD44." (PMID 34237321, 2021). "In the atherosclerosis model of apoE−/− mice, vascular expression of CD44 was highest in areas prone to damage." (PMID 34335086, 2021). "CD44 plays an essential role in developing and developing atherosclerosis by mediating inflammatory cell recruitment and vascular cell activation." (PMID 34138931, 2021).